FOXP3 (forkhead box P3)
Diseases named in the same sentence as FOXP3 in open-access papers (continued):
Sharing a sentence is not in itself a finding about the gene and the disease.
ht (1 paper, 2018). "The ratio of CD4+/CD8+ T cells was significantly increased in HT model mice, which reflects the abnormal immune reaction in HT model mice, and decreased CD25+Foxp3+ Tregs was also found in peripheral blood of HT model mice." (PMID 29541033, 2018). "CD25+Foxp3+ Tregs were also decreased in HT patients (p < 0.05)." (PMID 29541033, 2018). "In this study, we provided that decreased level of CD25+Foxp3+ Tregs in HT model mice related to increased early phase and total insulin secretion, and the reinfusion of CD25+Foxp3+ Tregs separated from peripheral blood of normal mice restored the insulin sensitivity in HT model mice." (PMID 29541033, 2018). "Therefore, we separated and transfused peripheral blood CD25+Foxp3+ Tregs from normal mice into HT model mice, and the treatment significantly increased CD25+Foxp3+ Tregs in both of peripheral blood and VATs." (PMID 29541033, 2018). "Increased ratio of CD4+/CD8+ T cells and decreased CD25+Foxp3+ Tregs meant that HT might induce abnormal immune reaction not only in thyroid gland, periphery but also VATs." (PMID 29541033, 2018). "To confirm the mechanism of CD25+Foxp3+ Tregs increased insulin sensitivity, we adopted CD25+Foxp3+ Tregs to HT model mice and administered mice with anti-CD25 antibodies after 3 days." (PMID 29541033, 2018). "In HT model mice, the transfusion of CD25+Foxp3+ Tregs decreased the level of InsAUC30/GluAUC30 and InsAUC120/GluAUC120." (PMID 29541033, 2018). "In HT model mice, CD25+Foxp3+ Tregs were decreased significantly in both of peripheral blood and VATs when compared with the control group, and Tregs in VATs are important to insulin sensitivity." (PMID 29541033, 2018). "To confirm the hypothesis, we expressed GFP in separated CD25+Foxp3+ Tregs (named GFP-CD25+Foxp3+ Tregs), and we transfused these GFP-CD25+Foxp3+ Tregs into HT model mice." (PMID 29541033, 2018).
hydatid disease (1 paper, 2021). "In the present study, we noted that the frequency of Foxp3+ T cell in spleen was decreased, meanwhile the levels of Th17-type cytokines were increased after the rAd-mIL-28B treatment, which showed a beneficial immune characteristic against hydatid disease." (PMID 34818327, 2021).
Hydrocephalus (1 paper, 2017). Hydrocephalus is an active distension of the ventricular system of the brain resulting from inadequate passage of CSF from its point of production within the cerebral ventricles to its point of absorption into the systemic circulation. "Here we show that α-SNAP hypomorph, hydrocephalus with hopping gait, Napahyh/hyh mice harbor significant defects in CD4 T cell gene expression and Foxp3 regulatory T cell (Treg) differentiation." (PMID 28492364, 2017).
Hyperinsulinemia (1 paper, 2023). An increased concentration of insulin in the blood. "In this scenario, our data suggest that hyperinsulinemia can compensate for the metabolic imbalances produced by inflammation and lipotoxicity, increasing the number of FoxP3+ Treg cells." (PMID 37026009, 2023).
hyperlipidemia (1 paper, 2021). "To characterize hyperlipidemia-induced transcriptomic reprogramming in splenic Tregs of ApoE–/– mice, we performed RNA-Seq on splenic CD4+Foxp3+ Tregs of ApoE–/– mice and WT mice." (PMID 34622804, 2021).
hyperplastic (1 paper, 2022). "In our study, the FoxP3+ Treg cells were present in almost similar proportion of PTC with LT (52%) and hyperplastic nodule with LT (53%) cases with a comparable median H score." (PMID 36518249, 2022).
hypersplenism (1 paper, 2014). Overactive functioning of the spleen, resulting in excessive destruction of blood cells. "Moreover, Guo and co-workers reported that T lymphocyte subsets (CD4+CD25+CD127 low/-Treg) and Foxp3 ratio was strongly increased in subjects affected by hypersplenism and PH." (PMID 24976841, 2014).
hypertriglyceridemia (1 paper, 2025). A laboratory test result indicating elevated triglyceride concentration in the blood. "Conversely, ACC1 suppression has been shown to increase Foxp3+ Tregs, and induce hypertriglyceridemia, possibly limiting its therapeutic value." (PMID 41030439, 2025).
idiopathic nephrotic syndrome (1 paper, 2021). Nephrotic syndrome for which no cause has been identified. "Moreover, our results are in agreement with those of prior studies: In a study of 38 children with idiopathic nephrotic syndrome (FSGS included) and in a study of 63 adult patients with IgAN, it was found that FOXP3+ Tregs renal tissue expression was rather common." (PMID 34336285, 2021).
infarction (1 paper, 2022). A localised pathological necrosis of tissue resulting from obstruction of the blood supply usually by a thrombus, an embolus, or vascular torsion. "It is well known that the number of CD4+CD25+Foxp3+ Tregs increases in the heart during the first day after infarction, indicating an antigen-independent migration of Tregs into the injured myocardium." (PMID 36066993, 2022).
interstitial cystitis (1 paper, 2006). A rare chronic debilitating urogenital disease characterized by urinary frequency, urgency, and pelvic pain. "In addition, both FOXp3 and NRSF seems to be downstream of Wnt-Frizzled signaling which was recently proposed to participate in the pathogenesis of interstitial cystitis." (PMID 16420690, 2006).
intestinal cancer (1 paper, 2019). "Nevertheless, our data indicate that ST2+ CD4+ FOXP3+ Tregs may also promote tumorigenesis in other murine models of CRC based on genetic ablation of tumor suppressor genes critically regulating intestinal cancer." (PMID 31165767, 2019). "Here, we establish that circulating FOXP3+ Tregs from patients with intestinal cancer upregulate ST2, and that ST2+ FOXP3+ Tregs show preferential accumulation in tumor versus non-tumor colonic tissues." (PMID 31165767, 2019).
intestinal polyposis (1 paper, 2012). "We demonstrate a paradoxically favorable effect of FoxP3+ T cells on patient survival that is supported by a study in the ApcMIN/+ mouse model of intestinal polyposis where adoptive transfer of Tregs was able to regress established tumors." (PMID 22879926, 2012).
intestinal schistosomiasis (1 paper, 2011). An intestinal infection that is caused by Schistosoma japonicum. "Thus, our study implicates CD4+CD25+FoxP3+Tregs as a source of regulatory pressure during chronic intestinal schistosomiasis and in the wider context, as suppressors of Th2-driven pathology in the colon." (PMID 21858239, 2011).
kidney tumor (1 paper, 2014). "In the present study, we identified Foxp3, a transcription factor usually expressed in TRegs, in kidney tumor-associated macrophages." (PMID 25264896, 2014). "In addition, depletion of Foxp3+ cells using diphtheria toxin in Foxp3DTR mice reduced the frequency of type-2 macrophages (M2) in kidney tumors." (PMID 25264896, 2014). "In addition to detection of Foxp3 at the protein level, we demonstrated, using two sensitive molecular techniques, the presence of Foxp3 mRNA in renal tumor infiltrating macrophages." (PMID 25264896, 2014).
Langerhans cell histiocytosis (1 paper, 2011). Langerhans cell histiocytosis (LCH) is a systemic disease associated with the proliferation and accumulation (usually in granulomas) of Langerhans cells in various tissues. "Patients with langerhans cell histiocytosis, a condition with uncontrolled proliferation of LCs, show expansion of Foxp3+ Treg populations, indicating a role of LCs in Foxp3+ Treg expansion." (PMID 21711933, 2011).
leukopenia (1 paper, 2018). "Individually, analysis of secondary outcomes revealed that FKBP2 c.-2110GG genotype carriers had higher risk of leukopenia, FKBP1A n.259+24936C allele carriers had increased risk of constipation, and FOXP3 c.-22-902A or c.-23+2882A allele had higher risk of gastrointestinal disorders (p < 0.05)." (PMID 30487748, 2018).
leukoplakia (1 paper, 2021). A white patch or plaque on a mucous membrane that cannot be characterized clinically or pathologically as any other disease. "In addition, a significantly greater abundance (cells/mm2) of FOXP3+ Tregs were observed among proliferative leukoplakia tissue samples at the dysplastic epithelium, the DSI, and in the stroma (D, 29.8 vs. 0.8; DSI, 265.7 vs. 24.2; S, 115.8 vs. 4.3; all P < 0.001)." (PMID 36860910, 2021).
lichen sclerosis (1 paper, 2022). "Similarly, different percentages of CD4+ and (forkhead box P3) FOXP3+ lymphocytes have a vital role in the etiopathogenesis of both female and male lichen sclerosis but have different pathogenetic pathways." (PMID 36176860, 2022).
liver neoplasm (1 paper, 2018). Tumors or cancers of the LIVER. "QRT‐PCR was used for assessment of FOXP3 expression in liver neoplasms tissues and para‐carcinoma tissues." (PMID 30378283, 2018). "In summary, FOXP3 is confirmed to have the capacity to suppress proto‐oncogene MYC in liver neoplasm by up‐regulating miR‐198 through binding to its promoter, while miR‐198 targets the 3′‐UTR of MYC mRNA to inhibit its translation." (PMID 30378283, 2018). "Our study aimed to explore the effects of FOXP3 expression on liver neoplasms cells and to further investigate the relationship between FOXP3 and proto‐oncogene MYC." (PMID 30378283, 2018). "The high expression of FOXP3 and, especially miR‐198, is verified to have strong suppression on liver tumor cells viability and proliferation, while promoted the apoptosis meanwhile." (PMID 30378283, 2018). "It showed an under‐regulated expression of FOXP3 in liver neoplasm tissues from qRT‐PCR results." (PMID 30378283, 2018). "Hence, we tried to connect miR‐198 with FOXP3 to see whether they are both involved in one pathway that related to liver neoplasm regulation." (PMID 30378283, 2018). "To determine the viability of liver neoplasm cells, we performed CCK‐8 assay and colony formation assay on NC cells and cells transfected with pcDNA3.1‐FOXP3 or si‐FOXP3." (PMID 30378283, 2018). "In our study, we examined the influence that FOXP3 had on MYC expression as well as the viability and the proliferation capacity of liver tumor cells in contrast with the adjacent tissues." (PMID 30378283, 2018). "Since miR‐198/FOXP3 has a strong suppression on tumor cells, more powerful alternative inhibitors that direct at these two sites could be developed to better inhibit the proto‐oncogene MYC expression for clinical liver neoplasm treatment." (PMID 30378283, 2018).
lobular breast cancers (1 paper, 2012). "However, an association of increased numbers of FOXP3+ intratumoral cells could be found in the her2/neu over-expressing molecular subtype (ER-, PR-, her2/neu+) of lobular breast cancers (p = 0.006)." (PMID 22471961, 2012). "Infiltrating FOXP3+ cells were detectable to a significantly higher extent within the tumor (4.0 ± 9.1 vs. 3.7 ± 14.4, p = 0.001) and in the stroma (4.2 ± 1.4 vs. 2.8 ± 6.1, p = 0.007) of ductal cancers as compared to lobular breast cancers." (PMID 22471961, 2012).
lupus erythematosus (1 paper, 2023). An autoimmune, connective tissue chronic inflammatory disorder affecting the skin, joints, kidneys, lungs, heart, and the peripheral blood cells. "Thus, in this study, we aimed to prove whether the Foxp3 expression and mutation are crucial in lupus erythematosus, through computational modelling and experimental approaches." (PMID 37998578, 2023).
Lymphatic Metastasis (1 paper, 2025). Transfer of a neoplasm from its primary site to lymph nodes or to distant parts of the body by way of the lymphatic system. "FOXP3 (p = 0.0017) and CD163 (p = 0.0316) expression levels were significantly higher in the Hematogenous Metastasis compared to both the Primary Tumor and Lymphatic Metastasis." (PMID 41179298, 2025).
Lynch syndrome (1 paper, 2021). An autosomal dominant hereditary neoplastic syndrome characterized by the development of colorectal carcinoma and a high risk of developing endometrial carcinoma, gastric carcinoma, ovarian carcinoma, renal pelvis carcinoma, and small intestinal carcinoma. "Lynch syndrome lesions, however, also possess immunosuppressive entities such as (a) alterations in MHC class I antigen presentation, (b) TGFβRII mutations, (c) upregulation of PD-L1 on tumor-associated T cells, and (d) tumor-associated FOXP3+ regulatory T cells." (PMID 34125344, 2021).
marginal zone lymphoma (1 paper, 2018). A usually indolent mature B-cell lymphoma, arising from the marginal zone of lymphoid tissues. "Both total numbers of activating follicular helper (Tfh) cells (defined by high expression of PD1) and suppressive regulatory (Treg) T-cells (defined by FOXP3+ expression) and the Tfh:Treg ratio, assessed over relatively large areas of tissue, varied among cases of marginal zone lymphoma." (PMID 30219078, 2018).
mastitis (1 paper, 2024). Inflammation of breast tissue during lactation or postpartum due to an obstructed duct or infection. "An evaluation of the association between FOXP3 variants (T-reg genotypes) and cysts, mastitis, and postpartum days open showed that the G/G genotype was associated with a significantly higher incidence of cysts (p = 0.017; with an additive model)." (PMID 38791678, 2024).
mismatch repair deficiency (1 paper, 2008). "In summary, this is the first study systematically examining the association of mismatch repair deficiency and infiltration with FOXP3-positive cells." (PMID 18985040, 2008).
monoclonal gammopathy of undetermined significance (1 paper, 2014). "Expression of markers for Treg (FOXP3, CTLA4) and Th17 cells (RORγt) was determined by quantitative real-time PCR in BM aspirates of 46 MM patients, four patients with monoclonal gammopathy of undetermined significance, five solitary plasmacytomas, and five healthy BM donors." (PMID 25099367, 2014).
mucinous tumors (1 paper, 2024). "For example, mucinous tumors displayed a more active immune response compared to the other low-grade carcinomas, with relatively higher levels of CD8 cytotoxic T cells and immune activation marker VISTA, while lower in immune suppressive markers (IDO1, FOXP3, CTLA4)." (PMID 39026018, 2024).
muscular dystrophies (1 paper, 2020). "In experimental murine models of muscular dystrophies characterized by membrane instability, blockade of eATP/P2X7 receptor (R) purinergic signaling delayed the progression of the dystrophic phenotype dampening the local inflammatory response and inducing Foxp3+ T Regulatory lymphocytes." (PMID 32825102, 2020).
mycoplasma infection (1 paper, 2016). "Treg cells (CD4+CD25+FoxP3+) preferentially expanded in the host after mycoplasma infection, suggesting that they do play a role in the disease." (PMID 27175511, 2016).
Myelodysplasia (1 paper, 2018). Clonal hematopoietic stem cell disorders characterized by dysplasia (ineffective production) in one or more hematopoietic cell lineages, leading to anemia and cytopenia. "The DNMT inhibitors Aza and DAC, which seemingly have the potential to promote FOXP3 expression, are therapeutically used in MDS, AML, and CMML patients to reduce uncontrolled myelodysplasia and increased survival of the patients." (PMID 29850630, 2018).
myelofibrosis (1 paper, 2021). A partial or complete replacement of the bone marrow stroma by fibrous tissue. "Internal consistency analysis regarding evaluation of the immunohistochemical markers yielded good or excellent results for myelofibrosis, nestin niches, CD34-positive blast counts, and counting of granzyme B, T-bet, FoxP3, CD3, CD4, CD8, and E-cadherin positive cells." (PMID 33704530, 2021).
myeloid leukemia (1 paper, 2024). A clonal proliferation of myeloid cells and their precursors in the bone marrow, peripheral blood, and spleen. "FoxP3 expression maintenance is controlled by the conserved non-coding sequence 2 (CNS2), which binds both acute myeloid leukemia-1 (AML1)/Runx1 and FoxP3 in mature Tregs." (PMID 38509593, 2024).
nasopharynx tumor (1 paper, 2022). "Larger primary nasopharynx tumor was found to be related to higher concentration of FOXP3 markers in local primary nasopharynx." (PMID 35963999, 2022).
neuroendocrine carcinoma (1 paper, 2022). A malignant neuroendocrine neoplasm composed of cells containing secretory granules that stain positive for NSE and chromogranin. "In addition, the Foxp3/CD8 (p = 0.0717) and the PD-1/CD8 ratios (p = 0.0176) (representing tumor immunity suppression) tend to increase in neuroendocrine carcinomas." (PMID 35565281, 2022).
neuromyelitis optica spectrum disorder (1 paper, 2024). "In the present study, we genotyped three single-nucleotide polymorphisms, namely, rs2232365, rs3761548, and rs3761549, to determine the relationship between FOXP3 polymorphisms and neuromyelitis optica spectrum disorder (NMOSD) susceptibility among the Northern Chinese Han population." (PMID 38584670, 2024).
neurosyphilis (1 paper, 2013). Infection of the brain or spinal cord by Treponema pallidum. "First, future studies should examine Foxp3 expression and define the functional status of CD4+ CD25high Tregs in CSF in neurosyphilis patients." (PMID 24244772, 2013).
neurotoxicity (1 paper, 2024). Toxicity that causes injury to the central or peripheral nervous system or damages its function. "Neurotoxicity was best predicted by CD25+ FoxP3+ GARP+ % (inversely)." (PMID 38750122, 2024).
nonalcoholic steatohepatitis (1 paper, 2025). "In metabolic disorders such as nonalcoholic steatohepatitis (NASH) and sepsis, NETs promote oxidative phosphorylation (OXPHOS) and cholesterol metabolism in naïve CD4+ T cells, thereby driving the differentiation of FOXP3+ regulatory T cells (Tregs) through TLR4 signaling." (PMID 40442839, 2025).
oral diseases (1 paper, 2020). "Formalin fixed paraffin-embedded tissue sections from different oral diseases were stained with PD-L1 and TILs (CD8+ T cells and FOXP3+ Tregs) by mIHC staining simultaneously." (PMID 33364188, 2020).
oropharyngeal tumors (1 paper, 2017). "Formalin-fixed, paraffin-embedded tissue from oropharyngeal tumors of 99 patients was immunohistochemically stained for PD-L1 (SP142 and 22C3 clones), CD3, CD8 and FoxP3." (PMID 29113315, 2017).